RNU6-38P (RNA, U6 small nuclear 38, pseudogene)
Synonyms: RNU6-38
Gene: Small nuclear RNA gene on chromosome 13 (75,109,587 to 75,109,693, forward strand). Ensembl gene ENSG00000206812.
Homologues: Orthologues: chimpanzee U6 (99% identical), rabbit U6 (97% identical), pig U6 (96% identical), guinea pig U6 (94% identical), dog U6 (87% identical), pig U6 (84% identical), mouse Gm23169 (83% identical), dog U6 (82% identical). Paralogues in human: RNU6-1145P (96% identical), RNU6-25P (96% identical), RNU6-29P (96% identical), RNU6-1 (95% identical), RNU6-1316P (95% identical), RNU6-2 (95% identical), RNU6-20P (95% identical), RNU6-39P (95% identical), RNU6-3P (95% identical), RNU6-4P (95% identical), RNU6-574P (95% identical), RNU6-5P (95% identical), and 1288 more.